Y_RNA (Y RNA )
Gene: Miscellaneous RNA gene on chromosome 8 (70,780,914 to 70,781,008, reverse strand). Ensembl gene ENSG00000223220.
Homologues: Orthologues: chimpanzee Y_RNA (100% identical), macaque Y_RNA (96% identical). Paralogues in human: RNY4 (85% identical), RNY4P3 (85% identical), Y_RNA (85% identical), RNY4P25 (83% identical), RNY4P7 (83% identical), Y_RNA (83% identical), RNY4P6 (82% identical), Y_RNA (82% identical), RNY4P14 (81% identical), RNY4P23 (81% identical), RNY4P10 (80% identical), RNY4P27 (80% identical), and 87 more.